CD4 (CD4 molecule)
Diseases named in the same sentence as CD4 in open-access papers (continued):
Sharing a sentence is not in itself a finding about the gene and the disease.
chlamydial infection (continued). "Although anti-CD4 + anti-NK1.1-treated mice were susceptible to reinfection, chlamydia shedding was less robust and the duration of infection was shorter than in primary infection of fully immunocompetent mice." (PMID 28739831, 2017). "Studies of protective immunity in the murine model of C. trachomatis genital infection demonstrated that an MHC class II restricted CD4+ Th1 response is critical for resolving primary chlamydial infection." (PMID 25551828, 2014). "Apart from the Th1-subset, little is known about the role of other CD4+ T cell subsets in response to a genital tract chlamydial infection." (PMID 21079691, 2010). "IL-10 producing cDCs following chlamydial infection of the lung have been shown to reduce allergen-specific cytokine production and CD4+ T cell responses." (PMID 21079691, 2010). "Apart from the Th1 cells, little is known about the role of other CD4+ T cell subsets in response to a genital tract chlamydial infection." (PMID 21079691, 2010). "The balance between CD4+ effector cell populations and Tregs is considered critical for limiting the immunopathological outcome of a chlamydial infection." (PMID 21079691, 2010). "Overall, our data suggests that Th1 mediated immune responses in CD4+ T cells can contribute to protection and clearance of genital chlamydial infection." (PMID 19698128, 2009). "Chlamydial infection of mice lead to the development of CD4+ T cells that significantly secreted IL-6, IL-10, and GM-CSF, but not IL-4, in response to C. muridarum re-stimulation." (PMID 18700040, 2008). "While little is known regarding Ag-specific CD4+ T cell (IL-4 and GM-CSF) secretory responses during Chlamydia infection, we show that these T helper cytokines were increased during chlamydial infection." (PMID 18700040, 2008). "Another pro-inflammatory cytokine, IL-17A, which is secreted by Th-17 CD4+ T cells, is involved in the host defense against microbial organisms, but its role in protecting ruminants from chlamydial infections is currently unknown." (PMID 40573940, 2025). "Additionally, T cells migrating to the female mouse genital tract following chlamydial infection were mostly CD4+ and expressed increased mucosal homing molecules LFA-1 (CD11a) and α4β7." (PMID 39203989, 2024). "Given the importance of CD4+ T-cells in adaptive immunity, this may be one factor effecting immunity to chlamydial infections." (PMID 39600869, 2024). "Memory CD4+ T cells play an important role in protection against subsequent chlamydial infections." (PMID 34249004, 2021). "In addition to the humoral immune response, we analyzed the CD4+ T-cell response, which is the most important adaptive immune response against chlamydia." (PMID 32630694, 2020). "In both mice and humans, CD4+ T cells are essential for the resolution of chlamydial infections." (PMID 31790512, 2019). "The immune response to chlamydia thus includes production of pro-inflammatory cytokines, followed by maturation of T cells into both CD4 and CD8 T cells (recognizing specific MHC-presented chlamydial antigens) and activation of B cells that will produce specific anti-chlamydial antibodies." (PMID 28575080, 2017). "Furthermore, studies on animal models have shown that local CD4+ cell response via the secretion of IFNγ and stimulation of other protective immune cells is required for a successful resolution of chlamydial infection." (PMID 28678871, 2017). "IFN-γ is secreted in large quantities by CD4+ T cells during chlamydial infection and is known to play a role in immunoglobulin class switching, B cell maturation, and activation of several immune cell populations and processes during bacterial infections (19, 31, –, 37)." (PMID 27600502, 2016). "Moreover, CD8 T cells also produce IFN-γ in response to chlamydial infection which complements the IFN-γ produced by CD4 T cells." (PMID 25253920, 2014).
chlamydial infection (continued). "Together, these observations suggest that the reduced susceptibility to chlamydial infection in the absence of IL-13 is not mediated by CD4+ T cells but is linked to the innate host defence response." (PMID 21573182, 2011). "However, their expression patterns in CD4+ T cells in our stress model during chlamydia genital infection yet is unknown." (PMID 32413046, 2020). "As CD4+ cells play an essential role in the control of chlamydial infection in both humans and the murine model, depletion of CD4+ cells or reduction in CD4 expression could also play a role in making KoRV infected koalas more susceptible to chlamydial infection and disease." (PMID 31371797, 2019). "During the early stage of genital chlamydial infection, NK cells are not only a primary source of IFN-γ but also pivotal in promoting a protective CD4+ Th1 immune response through the secretion of this cytokine." (PMID 41156830, 2025). "Collectively these studies suggest that CD8 T cells likely play a role in protective immunity to chlamydia, but temporal differences between CD8 and CD4 T cells in this protection are likely." (PMID 40165713, 2025). "Extensive data suggest that both CD4+ and CD8+ T cells are involved in controlling chlamydial infection." (PMID 41156830, 2025). "Overall, it has been shown that mucosal vaccines elicit CD4 TRM cells in the genital tracts of mice and that these cells likely contribute to accelerated resolution of chlamydial infection upon challenge." (PMID 39203989, 2024). "She tested positive for HIV-1 26 months after her initial positive chlamydia test (HIV-1 RNA 1990 copies, CD4 318 cells/mm3)." (PMID 38464490, 2024). "In particular, memory CD4+T cells can persist for a long time, proliferate rapidly and secrete cytokines such as IFN-γ during secondary chlamydial infection." (PMID 32626664, 2020). "Therefore, exploring the mechanisms that regulate β2-AR expression may lead to the development of methods for limiting Th1 or Th2 responsiveness to NE or β2-AR agonists that may lead to the development of CD4+T cells-mediated pathologies during chlamydia genital infection." (PMID 32413046, 2020). "It has been well-established that CD4+ Th1 response, particularly IFN-γ production, is essential for protective recall immunity to chlamydial infection in animal models." (PMID 32626664, 2020). "The number of IFN-γ+ CD4 T cells: TH1 cells, the lymphocytes primarily responsible for clearing chlamydial infections, was measured by FACS in the spleen (Spl), iliac lymph node (ILN), and the genital tract (GT) 7 days post infection." (PMID 29552679, 2017). "Studies in both human and mice have shown that both CD4+ and CD8+ cells are present at the site of chlamydial infection." (PMID 25386180, 2014). "In fact, it appears that bystander non-protective CD8+ and CD4+ T cells, recruited to the site of chlamydial infection through CXCR3, play a pivotal role in Chlamydia-induced immunopathology." (PMID 39204067, 2024). "However, previous studies have demonstrated that restricted CD4+ T cell primary histocompatibility complex class II (MHC-II) is required for protective immunity by vaccines, which enhance clearance of chlamydial infection by producing IFN-γ." (PMID 37108176, 2023). "While the role of CD4+ and CD8 + T cell-dependent mechanisms in protection against Chlamydia has been established, the relative contribution of antibody in the resolution of a primary chlamydial infection is still unfolding." (PMID 34001988, 2021). "Previous results in the lab show that CIS increases the intensity of chlamydia genital infection, but little is known about the effects and mechanisms of CIS on the differentiation and activities of CD4+ T cell subpopulations and bone marrow-derived dendritic cells (BMDCs)." (PMID 32413046, 2020).
chlamydial infection (continued). "Overall, CD4+ T cell depletion did not affect the recruitment of major immune populations to the genital tract at any time point during primary chlamydial infection in IFN-γ−/− or μMT mice." (PMID 27600502, 2016). "The level of CD4 count as well as the viral load did not seem to affect the prevalence of chlamydia in the study population." (PMID 26879379, 2016). "Indeed, studies of chlamydial infection in knockout mice support the importance of class II MHC, CD4, IL-12, IFN-γ, and IFN-γ receptor for chlamydial immunity." (PMID 18700040, 2008). "Mouse and nonhuman primate studies suggest IFN-γ-producing CD4+ T cells are needed for clearance of chlamydial infections, and the generation of appropriate type 1 immunity is often considered to be an integral component of any vaccine conferring protection against chlamydial disease expression." (PMID 22144851, 2011). "Firstly, the in-host models used here suggest that for frequent exposure to chlamydia, the formation of a proportional antibody response (i.e., TH1 TH2) is not only central for preventing reinfection, but for regulating an individual's CD4+ T cell populations as well." (PMID 19727394, 2009). "Patient 2 had 3 negative HIV tests and was subsequently diagnosed with chlamydia and HIV-1 concurrently (HIV-1 RNA 13 200 copies, CD4 416 cells/mm3)." (PMID 38464490, 2024). "Both CD4+ cells and macrophages release interferon gamma (IFN-γ), which can resolve chlamydial infection or stimulate a non-replicative persistent state that can result in chronic infection that is likely resistant to antimicrobial treatment." (PMID 20543948, 2010). "qPCR was used to examine mRNA expression for Th1 (IFNγ), Th2-promoting (IL6, IL10) and Th17 (IL17A) cytokines, along with CD4 and CD8 in whole blood of koalas (n = 74) from Mt Eccles and Raymond Island in Victoria, Australia, with and without natural chlamydial infection." (PMID 31371797, 2019). "Excluding HIV testing (and CD4 t-cell test) and TB testing, participants had never had the opportunity to undergo these tests offered in this study (e.g., HIV viral load and urogenital and anorectal gonorrhea and chlamydia testing) or to undergo TB testing at the same time as STI or HIV testing." (PMID 32413084, 2020).
cutaneous T-cell lymphoma (50 papers, 2005 to 2026). "The BACH2 gene is a transcription factor associated with cutaneous T-cell lymphoma, and its expression is suppressed in CD4-positive T cells." (PMID 38545443, 2024). "Although both cell lines (HuT78 and HH) derived from CD4+ cutaneous T-cell lymphomas are probably similar to normal CD4+ T cells, they lack mutations in TET2, DNMT3A, and IDH2 in contrast with the neoplastic cells of AITL." (PMID 37370838, 2023). "Sézary syndrome (SS) is a leukemic and incurable variant of cutaneous T-cell lymphoma characterized by the accumulation of neoplastic CD4+ lymphocytes in the blood, lymph nodes, and skin." (PMID 35740513, 2022). "Sézary syndrome (SS) is a rare and aggressive CD4+ leukemic variant of cutaneous T cell lymphoma (CTCL) with a disease-specific 5-year survival of 36% and median survival of 2–4 years." (PMID 36400759, 2022). "Cutaneous T-cell lymphoma (CTCL), a rare type of skin tumor, is a primary non-Hodgkin lymphoma that is mainly caused by the malignant clonal proliferation of skin-resident CD4+ T cells." (PMID 41614909, 2026). "Cutaneous T cell lymphomas are a rare form of non-Hodgkin lymphomas characterized by the accumulation of malignant CD4+ lymphocytes homing into the skin." (PMID 39409988, 2024). "The fact that malignant CD4+ T cells appear to be more sensitive to UVA1 radiation-induced apoptosis than normal CD4+ T cells supports the convenience of this treatment in the management of cutaneous T-cell lymphomas." (PMID 36983825, 2023). "Rare types of cutaneous T-cell lymphoma are primary cutaneous CD4+ small to medium T-cell lymphoma, primary cutaneous gamma/delta T-cell lymphoma, and primary aggressive cutaneous CD8+ cytotoxic epidermotropic T-cell lymphoma." (PMID 36363575, 2022). "It is also overexpressed in Sezary syndrome (SS), a rare, aggressive CD4+ cutaneous T-cell lymphoma." (PMID 36164519, 2022). "Sézary syndrome (SS) is an aggressive cutaneous T cell lymphoma with poor prognosis mainly characterized by the expansion of a tumor CD4+ T cell clone in both skin and blood." (PMID 36230895, 2022). "The particularity of this case report is represented by a rare case of cutaneous T-cell lymphoma, more accurately described as primary cutaneous CD4+ small to medium T-cell lymphoma, that has an overtly benign clinical course." (PMID 36363575, 2022). "Cutaneous T-cell lymphomas (CTCLs) include a large spectrum of mature T-cell neoplasms characterized by the accumulation of neoplastic CD4+ T lymphocytes in the skin." (PMID 35740513, 2022). "CD4+CD45RO+ T cells in the lesional blood expressed genes associated with the development of cancer and progression of cutaneous T-cell lymphoma." (PMID 34608214, 2021). "MF is the most common type of cutaneous T-cell lymphoma (CTCL), in which a protracted clonal expansion of atypical dermatotropic CD3+CD4+ T-lymphocytes underlies a chronic cutaneous manifestation." (PMID 34778050, 2021). "The cytolytic potential for CD4/CD8 DP T cells has been demonstrated in patients with cutaneous T cell lymphoma." (PMID 30709425, 2019). "Patient 1 presented with Sézary syndrome, an aggressive form of CD4+ cutaneous T-cell lymphoma unresponsive to standard chemotherapy." (PMID 29348865, 2017). "Due to the phenotypic similarity of CD4+CD25+ cutaneous T cell lymphoma cells and CD4+CD25+ TREG cells, Ontak was tested in many cancers." (PMID 24904823, 2014). "In summary, the CD4 marker is characteristic of cutaneous T-cell lymphomas (CTCL) and the CD20 and CD79α markers are features of cutaneous B-cell lymphomas (CBCL)." (PMID 24063735, 2013). "Skin infiltrates of clonal CD3 positive, CD4 positive cells is characteristic of most cutaneous T-cell lymphomas (CTCL), whereas increased numbers of CD20 and CD79α positive cells in the skin are features of cutaneous B-cell lymphomas (CBCL)." (PMID 24063735, 2013).
cutaneous T-cell lymphoma (continued). "Malignant CD4+ T lymphocytes from patients with Sézary syndrome, an aggressive cutaneous T-cell lymphoma, express NCR1 mRNA and protein at the cell surface where it appears to display a novel inhibitory function." (PMID 22212381, 2012). "Recombinant IL-2/diphtheria toxin fusion protein (rIL-2/DTx), a drug that is FDA-approved for the treatment of cutaneous T cell lymphoma, has been reported to deplete regulatory CD4+ T cells." (PMID 21909452, 2011). "A humanized anti-CD4 depleting antibody has already demonstrated efficacy in patients with cutaneous T cell lymphoma, although its usefulness as immunotherapy against solid tumors remains to be explored." (PMID 22046294, 2011). "A further layer of complexity is added by the positive feedback between NLRP3 and the IL-4 promoter, particularly in malignant CD4+ T cells of cutaneous T cell lymphoma, which perpetuates high IL-4 production and reinforces the Th2-dominant, immunosuppressive environment." (PMID 40864740, 2025). "Cutaneous T-cell lymphoma (CTCL) is a heterogeneous malignancy characterized by the proliferation of skin-homing CD4+ T cells and profound immune dysregulation within the tumor microenvironment (TME)." (PMID 41614909, 2026). "Primary cutaneous CD4+ small/medium T-cell lymphoproliferative disorder (PCSM-TCLPD) is an uncommon, indolent lymphoid proliferation that can resemble more aggressive cutaneous T-cell lymphomas." (PMID 42299215, 2026). "Cutaneous T-cell lymphoma (CTCL) is a rare type of primary cutaneous lymphoma that derives from mature, skin-resident, or skin-homing CD4+ T-lymphocytes." (PMID 39123440, 2024). "Immunohistochemical results showed positivity for CD3, CD4, CD5, CD7, and CD8, indicating cutaneous T-cell lymphoma (CTCL) Sezary Syndrome." (PMID 40034934, 2024). "Cutaneous T cell lymphomas (CTCL) comprise most cases, with neoplastic cells commonly exhibiting a CD4+CD8- immunophenotype." (PMID 37654486, 2023). "In Sézary Syndrome (SS), an aggressive, rare form of cutaneous T-cell lymphomas (CTCL), circulating CD4+ T-cells show increased expression of PLS3, TWIST1 and GATA6 compared to normal CD4+ T-cells." (PMID 34023917, 2021). "Cutaneous T cell lymphoma (CTCL) is a malignant expansion of mature, clonal CD4 T cells with an affinity for epidermal localization." (PMID 16029505, 2005). "Sézary syndrome (SS) is a rare and aggressive type of cutaneous T-cell lymphoma (CTCL) characterized by an intense pruritus, erythroderma (>80% involvement of the body surface), and the systemic dissemination of clonal CD4+ T cells into the blood and, often, the lymph nodes." (PMID 36902104, 2023).